ADAP1 (ArfGAP with dual PH domains 1)
Description:
GTPase-activating protein for the ADP ribosylation factor family (Probable). Binds phosphatidylinositol 3,4,5-trisphosphate (PtdInsP3) and inositol 1,3,4,5-tetrakisphosphate (InsP4). Regulates the incorporation of CD63 and CD9 into multivesicular bodies.
Synonyms: CENTA1; GCS1L; p42IP4
Tractability: Small molecule: a structure with a bound ligand is known; it has a high-quality binding pocket. Antibody: its Gene Ontology location is reachable by antibodies, with high confidence. PROTAC: ubiquitination databases record sites on it; its protein half-life has been measured.
Gene: Protein-coding gene on chromosome 7 (897,900 to 955,407, reverse strand). Ensembl gene ENSG00000105963.
Subcellular location: Nucleus; Cytoplasm
Subcellular location (Human Protein Atlas): Cytosol; Plasma membrane
Pathways (Reactome):
Signal Transduction: Nuclear signaling by ERBB4
Gene Ontology:
Molecular function: GTPase activator activity; protein binding; inositol 1,3,4,5 tetrakisphosphate binding; phosphatidylinositol-3,4,5-trisphosphate binding; phosphatidylinositol bisphosphate binding
Biological process: regulation of GTPase activity; cell surface receptor signaling pathway
Cellular component: cytoplasm; cytosol; nucleus; plasma membrane
Genetic constraint (gnomAD): Loss-of-function variants: 31 observed, 44.1 expected, observed/expected ratio (o/e) 0.7, 90% interval 0.53 to 0.95. The synonymous counts are far from expectation, so gnomAD's model fits this gene poorly and the ratio says little. Missense variants: 535 observed, 462.06 expected, observed/expected ratio (o/e) 1.16, 90% interval 1.08 to 1.24. Synonymous variants: 313 observed, 186.15 expected, observed/expected ratio (o/e) 1.68, 90% interval 1.53 to 1.85.
Homologues: Orthologues: mouse Adap1 (94% identical), dog ADAP1 (94% identical), pig ADAP1 (91% identical), rat Adap1 (89% identical), guinea pig ADAP1 (88% identical), tropical clawed frog adap1 (78% identical), macaque ADAP1 (72% identical), chimpanzee ADAP1 (71% identical). Paralogues in human: ADAP2 (57% identical), ARAP3 (26% identical), ARAP1 (26% identical), ARAP2 (25% identical), SMAP1 (25% identical), SMAP2 (23% identical), AGAP2 (21% identical), ASAP2 (21% identical), AGFG1 (21% identical), AGAP1 (20% identical), ACAP3 (19% identical), AGAP3 (19% identical), and 16 more.
Diseases named in the same sentence as ADAP1 in open-access papers:
ADAP1 is named in the same sentence as 21 diseases in open-access papers, as found by Europe PMC text mining. Sharing a sentence is not in itself a finding about the gene and the disease. The quoted sentences say what the papers report.
Alzheimer disease (2 papers, 2021 to 2025). A progressive, neurodegenerative disease characterized by loss of function and death of nerve cells in several areas of the brain leading to loss of cognitive function such as memory and language. "ADAP1/Centaurin-α1 (CentA1) is highly enriched in the brain, and an increased CentA1 level has been linked to Alzheimer's disease (AD)." (PMID 41249052, 2025). "ADAP1/Centaurin-α1 (CentA1) is an Arf6 GAP, which is known as a regulator dendritic differentiation and a potential mediator of Alzheimer’s disease (AD) pathogenesis." (PMID 33139322, 2021).
cardiac hypertrophy (1 paper, 2022). "Another gene, Adap1, which encodes the GTPase-activating protein ArfGAP with dual PH domain 1 and is linked to cardiac hypertrophy, was also upregulated." (PMID 36377660, 2022).
colorectal cancer (1 paper, 2021). A primary or metastatic malignant neoplasm that affects the colon or rectum. "DSVs in SGSM2 and LHFPL3 were relevant to colorectal cancer, whereas ADAP1, DLGAP2, ERC1, and PPP6R2 were related to gynecologic cancer." (PMID 33431054, 2021).
heart failure (1 paper, 2022). Inability of the heart to pump blood at an adequate rate to meet tissue metabolic requirements. "Here, we observed that the level of CNPase and ADAP1 increased in RBM isolated from rats after heart failure, while AST abolished the effect of ISO and the protein levels decreased." (PMID 36613474, 2022).
lymphoma (1 paper, 2022). A malignant (clonal) proliferation of B- lymphocytes or T- lymphocytes which involves the lymph nodes, bone marrow and/or extranodal sites. "Consistently, scRNAseq predicted abnormal leukocyte and lymphoma phenotypes upon ADAP1 loss in stimulated TM, further suggesting ADAP1 has a role in tuning the identity and magnitude of T cell gene programs to avoid malignancy." (PMID 35232997, 2022).
multiple sclerosis (1 paper, 2019). A progressive autoimmune disorder affecting the central nervous system resulting in demyelination. "NFASC is involved in multiple sclerosis, and ADAP1 is involved in AD." (PMID 31333395, 2019).
squamous cell carcinoma (1 paper, 2019). A carcinoma arising from squamous epithelial cells. "ADAP1, a GTPase-activating protein (GAP) for the small GTPase ARF6, is a strong predictor of poor survival in early-stage squamous cell carcinoma patients and a critical mediator of TGF-β-induced invasive cell migration by facilitating basement membrane breakdown." (PMID 31792062, 2019).
cancer (6 papers, 2019 to 2023). A tumor composed of atypical neoplastic, often pleomorphic cells that invade other tissues. "ADAP1 also encodes for a GTPase-activating protein involved in cancer progression and brain memory function." (PMID 37626570, 2023). "A clonogenic assay was performed to determine the effect of the ADAP1‐NOC4l on the proliferation of cancer cell line SW48." (PMID 35702822, 2023). "The top DEGs upregulated in AA was endoplasmic reticulum-associated protein ZDHHC1, implicated in innate immune response and a positive regulator of the STING pathway, and ADAP1, which has been shown to promote cancer progression by inducing cell migration and invasion." (PMID 37732899, 2023). "Our study demonstrates that ADAP1 is a critical mediator of TGF-β-induced cancer invasion and might be exploited for the treatment of high-risk SCC." (PMID 31792062, 2019). "In comparison with other ArfGAPs, ADAP1 may be of particular importance to cancer progression, as it also has a GAP-independent role in actin cytoskeleton remodeling via its C-terminal dual pleckstrin homology domains." (PMID 31792062, 2019). "We also examined the role of ADAP1 in human cancer cell invasion in vitro." (PMID 31792062, 2019). "With ADAP1’s ability to tune the KRAS–ERK–AP-1 pathway, which is involved in several pathologies including cancer, an ADAP1-specific compound would be worth exploring beyond HIV-1 latency reversal." (PMID 35232997, 2022). "Hypo-methylated gDMs like MX2, OAS2, SPRED2, ADAP1, and SLC17A9 genes showed significant increased expression in cancer stage IV compared to stage I." (PMID 36329447, 2022). "Consistent with the previous studies showing that the ARF6-CA mutant suppresses the invasive activity of cancer cell lines, forced expression of the ARF6-CA mutant in ADAP1-overexpressing cells reduced the invasive activity, whereas ARF6-WT did not affect." (PMID 31792062, 2019).
infection (2 papers, 2015 to 2018). The state of being infected such as from the introduction of a foreign agent such as serum, vaccine, antigenic substance or organism. "To determine the influence of ACAP1, ADAP1, and ASAP1 on Salmonella remodeling of the cytoskeleton, we examined Salmonella invasion after a 15-min infection of Caco cells individually expressing recombinant hemagglutinin (HA)-tagged Arf GAPs." (PMID 25670778, 2015). "Increasing the overexpression of ADAP1 up to a multiplicity of infection (MOI) of 100 did not further increase the number of α-actinin puncta (data not shown)." (PMID 30206251, 2018).
tumor (1 paper, 2019). "TGF-β-responding tumor cells up-regulated ADAP1 at the tumor-stroma interface, which raised the possibility that ADAP1 may activate a molecular pathway that underlies TGF-β-induced invasive tumor progression." (PMID 31792062, 2019). "In postnatal mice, lentivirally transduced skin keratinocytes express YFP, in which the oncogenic HRASG12V transgene and ADAP1 are expressed in a Dox-dependent manner to induce tumor formation." (PMID 31792062, 2019). "Using a mouse model of SCC, we show that ADAP1 overexpression promotes invasive tumor progression by facilitating cell migration and breakdown of the basement membrane." (PMID 31792062, 2019). "Then, we found that ADAP1 also promotes invasion on a cell-by-cell basis in vitro and, more importantly, invasive tumor growth on a tissue basis in vivo." (PMID 31792062, 2019). "Overall tumor morphology assessed by hematoxylin and eosin (H&E) showed that ADAP1-overexpressing tumors were highly invasive, in which a significant ADAP1 expression was confirmed in tumor epithelial cells." (PMID 31792062, 2019). "Together, our study establishes ADAP1 as a potential prognostic marker and provides novel insights into the molecular pathway of invasive tumor progression." (PMID 31792062, 2019). "To delete the Adap1 gene in tumor cells in vivo, we performed in utero injection of the TGF-β reporter lentiviral vectors in Adap1fl/fl mice, and in Adap1+/fl or Adap1+/+ mice as controls." (PMID 31792062, 2019). "However, the quantification data revealed that TGF-β-responding tumor cells in Adap1 cKO tumors had significantly less cytoplasmic laminin compared with TGF-β-responding cells in control tumors." (PMID 31792062, 2019). "To determine whether ADAP1 is involved in invasive tumor growth and laminin internalization by TGF-β-responding tumor cells, we established an Adap1-floxed mouse line." (PMID 31792062, 2019). "To address this, we overexpressed the ADAP1-R49K mutant in tumor cells." (PMID 31792062, 2019). "Moreover, in ADAP1-overexpressing tumors, the other major component of the BM, type IV collagen, was almost undetectable at tumor-stroma interface, whereas collagen staining surrounding the vasculature remained (middle)." (PMID 31792062, 2019). "Furthermore, in accordance with our RNA-seq data, TGF-β-responding tumor basal cells had significantly stronger cytoplasmic staining of ADAP1 protein." (PMID 31792062, 2019). "However, in both mouse and human tumors, we detected ADAP1 protein expression in tumor cells at the leading edges of invasive tumors." (PMID 31792062, 2019). "Elucidating the fate and function of internalized laminin-binding integrins and the precise molecular mechanism of ADAP1-mediated laminin internalization may provide further insight into invasive tumor growth." (PMID 31792062, 2019). "Moreover, Adap1 deletion in tumor cells ameliorated the basement membrane breakdown and had less invading cells in the stroma." (PMID 31792062, 2019). "Decreased size in Adap1 cKO tumors suggested that ADAP1 might break a barrier for restricting extensive tumor growth." (PMID 31792062, 2019). "Interestingly, although tumors overexpressing a GAP activity-deficient mutant of ADAP1 resulted in morphologically complex tumors, those tumor cells failed to breach the basement membrane." (PMID 31792062, 2019). "Although other ARF6 GAPs and guanine nucleotide-exchanging factors (GEFs) might also regulate the potential laminin internalization, these results indicate that ADAP1 promotes invasive migration of TGF-β-responding tumor cells by facilitating the breakdown of the BM." (PMID 31792062, 2019). "We next asked whether the GAP activity of ADAP1 is involved in invasive tumor formation in vivo." (PMID 31792062, 2019). "We revealed that ADAP1-rich, TGF-β-responding tumor cells had laminin-332 in the cytoplasmic space, and simultaneously lost the BM composed of laminin and type IV collagen." (PMID 31792062, 2019).
tumor (continued). "We found that ADAP1-rich, TGF-β-responding tumor cells exhibit cytoplasmic laminin localization, which correlated with the absence of laminin and type IV collagen from the pericellular basement membrane." (PMID 31792062, 2019). "Here, we identify ADAP1, a GTPase-activating protein (GAP) for ARF6 up-regulated in TGF-β-responding invasive tumor cells, as a strong predictor of poor survival in early-stage SCC patients." (PMID 31792062, 2019). "Consistent with our in vitro data, these results suggest that ADAP1 plays both GAP activity-dependent and GAP activity-independent roles in invasive tumor growth in vivo." (PMID 31792062, 2019). "Interestingly, ADAP1-overexpressing, YFP+ tumor cells often exhibited laminin-332 in the cytoplasmic space (insets 3 and 4)." (PMID 31792062, 2019). "Interestingly, ADAP1-rich, TGF-β-responding tumor cells exhibited cytoplasmic laminin localization and disrupted the BM of their pericellular regions, which was mitigated by Adap1 deletion." (PMID 31792062, 2019). "Because Adap1 had the greatest fold up-regulation in TGF-β-responding tumor cells compared with nonresponding counterparts in our murine model, we focused on ADAP1 in this study." (PMID 31792062, 2019). "However, the role of ADAP1 in tumorigenesis and its contribution to ARF6-mediated tumor progression had not previously been evaluated." (PMID 31792062, 2019).
ADAP1 also shares sentences with these, for which no sentence is quoted: acute myeloid leukemia (1 paper); amyloid (1); Anxiety (1); brain disorder (1); Cognitive impairment (1); dysgerminoma (1); germinoma (1); gynecologic cancer (1); immune disorders (1); neurodevelopmental disorder (1); seminoma (1).